EFNA4 (ephrin A4)
Diseases named in the same sentence as EFNA4 in open-access papers (continued):
Sharing a sentence is not in itself a finding about the gene and the disease.
tumor (24 papers, 2017 to 2026). "EFNA4 has been associated with aggressive tumor behavior and is expressed in tumor-initiating cells (TICs), making it a compelling target for ADCs designed for targeted cytotoxic delivery." (PMID 41347223, 2025). "The targeting of EPHA2, EPHA10, EPHB4, ephrin-A2, ephrin-A4, as well as ephrin-B2 in BC cells or xenograft models is associated with apoptosis induction, tumor regression, anticancer immune response activation, and impaired cell motility." (PMID 36499598, 2022). "Furthermore, targeting of EPHA10, EPHB4, ephrin-A2, and ephrin-A4, as well as ephrin-B2 in BC cells or xenograft models was associated with tumor regression, anticancer T-cell activation, and impaired cell motility." (PMID 36499598, 2022). "Using a one-sample, two-tailed t-test, we analysed RNA-seq data from the TCGA-STAD, GSE79973, and GSE19826 databases to compare the expression levels of EFNA4 between tumour and normal tissue samples." (PMID 41162582, 2025). "We constructed a tumour-based risk signature for GC based on EFNA4, ETS1, and marker genes of the tumour cell cluster." (PMID 41162582, 2025). "In contrast, EFNA4 negatively correlated with these immune checkpoints, further highlighting its potential inhibitory role in tumour progression and immune evasion." (PMID 41162582, 2025). "The focus on EFNA4 as a therapeutic target is supported by its elevated expression in aggressive tumor cell populations across various cancers." (PMID 41347223, 2025). "Prognostic models for GC have been developed and tested based on the marker genes of tumour cell clusters or endothelial cells, EFNA4 and ETS1, and the former can better evaluate the prognosis of patients with GC." (PMID 41162582, 2025). "To address the challenges posed by tumour heterogeneity and reveal the expression patterns of EFNA4 and ETS1 in GC tissues, we performed reanalysis of single-cell RNA sequencing (scRNA-seq) data of GC samples." (PMID 41162582, 2025). "The expression patterns of ETS1 and EFNA4 in the AGC tumour cell subclusters were similar to those in the EGC tumour cell subclusters." (PMID 41162582, 2025). "Downregulation of EFNA4 in these cells can lead to a more aggressive tumour phenotype owing to altered cellular functions." (PMID 41162582, 2025). "EFNA4 is highly expressed in multiple tumor types, especially in LUAD, compared with paired normal tissues." (PMID 36077763, 2022). "Conversely, EFNA4 knockdown or knockout led to the growth suppression of cells and tumor xenografts in mice." (PMID 36077763, 2022). "On the one hand, targeting EFNA4 does show anti-tumor activity; on the other hand, patients show limited responses and numerous side effects." (PMID 36077763, 2022). "Immunohistochemical data from the Human Protein Atlas (HPA) database also showed that EFNA4 was highly expressed in the tumor." (PMID 36077763, 2022). "PF-06647263, an anti-ephrin-A4 antibody–drug conjugate, achieved sustained tumor regression in OC patient-derived xenografts in vivo." (PMID 35328669, 2022). "Then, we assessed EFNA4 copy number variation (CNV) in patients and found that EFNA4 is amplified in many tumor types." (PMID 36077763, 2022). "High expression of EFNA3, EFNA4, and EFNB1 was associated with tumor progression and worse prognosis in HCC patients." (PMID 36052169, 2022). "Subsequently, IHC and H&E staining was performed on the tumor tissue; N-cadherin was upregulated, whereas E-cadherin was downregulated in the EFNA4 overexpression tumor tissues." (PMID 34484860, 2021). "Compared with the empty vector group, the tumor proliferation index Ki67 was significantly increased in the EFNA4 overexpression group." (PMID 34484860, 2021). "More tumor nodules with fluorescence appeared in the liver of mice in the EFNA4 overexpression group." (PMID 34484860, 2021). "The expression of LUM and VCAN negatively correlated with tumor purity, whereas the expression of EFNA4 positively correlation with tumor purity." (PMID 34093807, 2021).
tumor (continued). "Several research studies found that the abnormal expression of EFNA4 was related to the occurrence of multiple tumor metastases." (PMID 34484860, 2021). "In our study, single-cell sequencing results were used to study the use of tumour cell markers with a high proportion in cancer tissues, as well as EFNA4 and ETS1, in order to construct a prognostic model that can better predict the prognosis of patients with GC." (PMID 41162582, 2025). "Despite EFNA4 showing oncogenic effects in liver and lung cancer, its dual role in GC (tumor suppressive and improved prognosis) remains unclear and requires further exploration." (PMID 41162582, 2025). "EFNA4 is involved in various tumour signalling pathways, whereas ETS1 is linked to tumour immunity and is positively correlated with fibroblast-related genes, contributing to chemotherapy resistance in low-purity tumours." (PMID 41162582, 2025). "RT-qPCR analyses of these tumor xenografts validated the over-expression of EFNA4." (PMID 36077763, 2022). "In brief, it can be concluded that high expression of EFNA3, EFNA4, and EFNB1 may be relevant to more gene mutations and, thus, drive oncogenesis and tumor progression of HCC." (PMID 36052169, 2022). "In addition to glycolysis, EFNA4-high tumor cells are more metabolically active than EFNA4-low tumor cells in many other metabolic pathways, including the tricarboxylic acid cycle, oxidative phosphorylation, fatty acid metabolism, and so on." (PMID 36077763, 2022). "We discovered that EFNA3, EFNA4, and EFNB1 were highly expressed in HCC tissues compared with normal samples, and the high expression of these genes was associated with tumor progression and vascular invasion and, thus, led to poor prognosis in patients with HCC." (PMID 36052169, 2022). "The stable EFNA4-overexpression A549 cell line and wild type cells were subcutaneously injected into the nude mice, and the corresponding transplanted tumor was formed after continuous feeding for 30 days, and the size and weight of each transplanted tumor were measured." (PMID 36077763, 2022). "Therefore, all those three useful prognostic indicators, LUM, VCAN, and EFNA4 are considered to have a relationship with the immunoregulation of the tumor environment." (PMID 34093807, 2021). "In contrast, EFNA4 negatively correlated with the six types of tumor-infiltrating immune cells." (PMID 34093807, 2021). "All mice were euthanized 30 days later to verify the effects of EFNA4 on tumor cell migration." (PMID 34484860, 2021). "Moreover, upregulation of EFNA4 promoted the penetration of the basement membrane by tumor cells, thereby facilitating cell migration (p < 0.001)." (PMID 34484860, 2021). "We used a mouse subcutaneous tumor model to further confirm the influence of EFNA4 in vivo." (PMID 34484860, 2021). "Interestingly some marker (e.g., EFNA4, GGH) also depicted over-expression in other cancers indicating their association with tumor development and progression related hallmark processes." (PMID 33133160, 2020). "An antibody-drug conjugate targeting Ephrin A4, named PF-06647263, consisting of a humanized monoclonal antibody anti-Ephrin A4 conjugated to the DNA-damaging agent calicheamicin, has been developed and tested to induce tumor regression in TNBC xenografts in vivo." (PMID 31330794, 2019). "Additionally, EFNA4 knockout significantly decreased the total tumor weights and size." (PMID 36077763, 2022). "The present clinical data suggested that EFNA4 may promote tumor progression." (PMID 34484860, 2021). "Under expression of EFNA4 may mitigate tumor neovascularization and enhance sorafenib efficacy." (PMID 28792525, 2017). "In tumour cells extracted from EGC and AGC scRNA-seq data, the expression of EFNA4 and ETS1 changed during pseudotime development." (PMID 41162582, 2025). "Our study has elucidated the distinct roles of EFNA4 and ETS1 in GC, as well as their expression patterns in tumour cells at the single-cell level." (PMID 41162582, 2025).
tumor (continued). "The expression of EFNA4 and ETS1 is depicted in the UMAP and violin plots, and ETS1 was significantly upregulated in tumour and endothelial cells." (PMID 41162582, 2025). "Most notably, the percentage of tumour cells with high ETS1 and low EFNA4 expression was higher in AGC than in EGC." (PMID 41162582, 2025). "We then performed a thorough study using the TISIDB database to further elucidate immune checkpoint correlations and the relationship between EFNA4, ETS1, and tumour immunity in the context of GC." (PMID 41162582, 2025). "In order to further identify the expression of EFNA4 and ETS1 during tumour cell differentiation, we analysed EGC and AGC tumour cells." (PMID 41162582, 2025). "Since ephrin-A4 was shown to be abundant in tumour-inducing or stem-like cells in triple-negative (TN) breast and ovarian patient-derived tissues, an ADC against ephrin-A4 was created using the humanised mAb E22 fused to the DNA-damaging agent calicheamicin." (PMID 36830852, 2023). "The results indicated that EFNA2 expression correlated with tumor residue; the expression of EFNA3 and EFNA4 correlated with age; EFNA5 expression correlated with the number of pack-years smoked." (PMID 35945523, 2022). "In HCC, the expression levels of EFNA1, EFNA3, EFNA4, EFNB1, and EFNB2 were significantly higher in tumor tissues than in normal tissues." (PMID 36052169, 2022). "Analogously, EFNA4 was negatively correlated with stromal scores (R = −0.24, p = 2.4e-06) and ESTIMAT scores (R = −0.16, p = 0.0015) but positively correlated with tumor purity (R = 0.16, p = 0.0015)." (PMID 36052169, 2022). "In Ephrin receptors, EFNA4 was conserved in EGFR-mut and KRAS-mut tumor while EFNA3 was conserved in EGFR-mut and NEK tumors." (PMID 36612014, 2022). "The expression of EFNA1, EFNA3, EFNA4, EFNB1, and EFNB2 was significantly increased in tumor tissues compared with normal tissues." (PMID 36052169, 2022). "We found that the expression of EFNA1, EFNA2, EFNA3, EFNA4, EFNB1, and EFNB2 was upregulated in the tumor tissues of most cancers compared with corresponding normal tissues." (PMID 36052169, 2022). "Signaling by EPHA10 and its ligand, EFNA4, promotes OSCC cell migration and tumor spheroid formation through induction of NANOG mRNA expression via ERK activation." (PMID 33436772, 2021). "Based on subgroup analysis using clinicopathological features (tumor grade and cancer stage), we found that VCAN, EFNA4, and LUM have significantly higher expressions in patients with tumor grade than in healthy individuals." (PMID 34093807, 2021). "Among these genes, EFNA4 and TEDC2 were significantly upregulated, whereas CDC42EP2, STX11, THBD, TMEM88, and GPM6A were notably downregulated in tumor tissues compared with adjacent normal tissues." (PMID 42196266, 2026). "Tumour and endothelial cell clusters comprised a relatively large proportion of the total number of cells captured in EGC and AGC tissues, accompanied by changes in ETS1 and EFNA4 in EGC and AGC." (PMID 41162582, 2025). "This evidence further substantiated the opposite effects of EFNA4 and ETS1 in the context of tumour immunity, playing an important role in immune cell-related pathways, and suggesting that they may affect the progression of GC through T cell exhaustion." (PMID 41162582, 2025). "Taken together, we have demonstrated that the expression of EFNA4 and ETS1 may influence the differentiation and characteristics of tumour cells, thereby affecting the progression of GC." (PMID 41162582, 2025). "Furthermore, in vitro and in vivo biological function experiments revealed that overexpression of EFNA4 promoted DNA replication, EMT, and tumor migration in HCC cells." (PMID 34484860, 2021). "A negative correlation was observed between the expression of EFNA4 and the six types of tumor-infiltrating immune cells." (PMID 34093807, 2021).
tumor (continued). "We assessed EFNA4 protein level in both tumor tissue and corresponding noncancerous epithelia in OSCC samples by immunohistochemical staining (IHC)." (PMID 33436772, 2021). "Given that the PI3K-AKT pathway can target ETS1 to promote tumor progression in multiple cancers, and ETS1 has been demonstrated to drive epithelial-mesenchymal transition (EMT), this study hypothesizes that EFNA4 may inhibit the PI3K-AKT signaling axis, thereby counteracting ETS1-mediated EMT." (PMID 41162582, 2025). "In short, these findings suggest that some ephrin genes (EFNA3, EFNA4, and EFNB1) are closely related to malignant biological behavior, such as tumor growth, vascular invasion and distant metastasis, and, thus, could be used as promising diagnostic and prognostic biomarkers in patients with HCC." (PMID 36052169, 2022). "Also, tumor/nontumor (T/N) ratios of EFNA4, NANOG, OCT4, and EPHA10 mRNA expression had averages of 1.39, 1.25, 2.37, and 1.03, respectively." (PMID 33436772, 2021). "EFNA4 is not expressed on immune cells but is expressed on tumor cells." (PMID 34093807, 2021). "Moreover, 75% of OSCC specimens demonstrated higher EFNA4 expression in tumor regions than in noncancerous regions." (PMID 33436772, 2021). "Both EFNA4 and ETS1 were overexpressed in GC tissues, with a negative correlation seen between their expression levels in GC tumour samples, suggesting a regulatory relationship." (PMID 41162582, 2025).
cancer (19 papers, 2015 to 2025). A tumor composed of atypical neoplastic, often pleomorphic cells that invade other tissues. "ETS1 is a transcription factor that is often associated with immune suppression and cancer cell proliferation, whereas EFNA4 may play different roles in immune regulation and intercellular interactions." (PMID 41162582, 2025). "EFNA4 belongs to the ephrin family, which anchors to the membrane via glycosylphosphatidylinositol linkage to mediate cancer cell growth, migration, and invasion." (PMID 35805033, 2022). "The results showed that EFNA1 and EFNA4 had the highest expression in pan-cancer, followed by EFNA3 and EFNA5 with high expression, and EFNA2 with low expression." (PMID 35309935, 2022). "Several recent studies have confirmed the role of EFNA4 in the progression of proliferation and metastasis of various cancers." (PMID 35945523, 2022). "In OSCC cells, EPHA10 plays a critical role in linking external stimuli (EFNA4 or other ligands) to the internal signal transduction that leads to cancer cell migration and spheroid formation." (PMID 33436772, 2021). "Several genes (for example, RIPK2, EFNA4 and TMEM9B) showed differential expression in subtypes associated with high proliferation, such as IntClust 5 (predominantly HER2/ERBB2-amplified cancers) and IntClust 10 (predominantly basal expression type cancers)." (PMID 25572802, 2015). "In the majority of cancers, EFNA1, EFNA2, EFNA3, and EFNA4 were suppressed by stromal and/or immune components, whereas EFNA5 demonstrated different trends in the stromal and immune scores across different cancers." (PMID 35945523, 2022). "The correlation of EFNAs co-expression at transcriptome level in pan-cancer was first examined, and the results suggested a strong correlation between EFNA1, EFNA3, and EFNA4." (PMID 35945523, 2022). "A positive correlation was noted between the expression of EFNA1, EFNA3, EFNA4, EFNA5 and CNV in most cancer types; however, EFNA2 expression was only weakly correlated with CNV." (PMID 35945523, 2022). "Based on RNA expression data, EFNA1 and EFNA5 were negatively correlated with the stem cell scores in most cancers, whereas EFNA2, EFNA3, and EFNA4 exhibited varying correlations with stem cell scores in different cancers." (PMID 35945523, 2022). "Spearman’s correlation analysis revealed a negative correlation between ETS1 and EFNA4 expression in a cohort of 407 GC samples from the TCGA Cancer Atlas." (PMID 41162582, 2025). "Noticeably, new potential targets including proteins expressed by cancer stem cells (CSC), such as PTK7, ephrin-A4, 5T4 and in the TME, such as CD205, CD25, B7-H3, are under investigation with some of these that already reached clinical phases of drug development." (PMID 35953604, 2022). "Additionally, Ephrin receptors including EFNA4 belong to tyrosine kinase family, SATB1 and CRNDE have been shown to be elevated in CRC and other cancers, which lead to poor prognosis and metastasis." (PMID 32041340, 2020).
cardiovascular disease (1 paper, 2022). "At the same time, the peptide also regulated the expression of the Efna4 and Taok3 genes in the MAPK signaling pathway, which has important functions in cardiovascular disease, can repair vascular injury, and is involved in cardiac remodeling." (PMID 35479750, 2022).
EFNA4 also shares sentences with these, for which no sentence is quoted: lung adenocarcinoma (2 papers); oral squamous cell carcinoma (2); autism (1); breast tumor (1); cervical cancer (1); cholangiocarcinoma (1); colorectal cancer (1); demyelination (1); endometrial cancer (1); fibromyalgia (1); gastric tumour (1); glioblastoma (1); hematologic cancers (1); hematologic malignancies (1); infection (1); lymphocytic leukemia (1); medulloblastoma (1); neuroblastoma (1); neuropathies (1); osteosarcoma (1); prostate carcinoma (1); psychiatric diseases (1); rhabdomyosarcoma (1); rheumatic disease (1); Sagittal craniosynostosis (1); Sjögren’s syndrome (1); systemic sclerosis (1); ulnar-mammary syndrome (1); uterine sarcoma (1); viral infection (1).